PIP5K1A (phosphatidylinositol-4-phosphate 5-kinase type 1 alpha)
Description:
Catalyzes the phosphorylation of phosphatidylinositol 4-phosphate (PtdIns(4)P/PI4P) to form phosphatidylinositol 4,5-bisphosphate (PtdIns(4,5)P2/PIP2), a lipid second messenger that regulates several cellular processes such as signal transduction, vesicle trafficking, actin cytoskeleton dynamics, cell adhesion, and cell motility. PtdIns(4,5)P2 can directly act as a second messenger or can be utilized as a precursor to generate other second messengers: inositol 1,4,5-trisphosphate (IP3), diacylglycerol (DAG) or phosphatidylinositol-3,4,5-trisphosphate (PtdIns(3,4,5)P3/PIP3). PIP5K1A-mediated phosphorylation of PtdIns(4)P is the predominant pathway for PtdIns(4,5)P2 synthesis (By similarity). Can also use phosphatidylinositol (PtdIns) as substrate in vitro. Together with PIP5K1C, is required for phagocytosis, both enzymes regulating different types of actin remodeling at sequential steps (By similarity). Promotes particle ingestion by activating the WAS GTPase-binding protein that induces Arp2/3 dependent actin polymerization at the nascent phagocytic cup (By similarity). Together with PIP5K1B, is required, after stimulation by G protein coupled receptors, for the synthesis of IP3 that will induce stable platelet adhesion (By similarity). Recruited to the plasma membrane by the E-cadherin/beta-catenin complex where it provides the substrate PtdIns(4,5)P2 for the production of PtdIns(3,4,5)P3, IP3 and DAG, that will mobilize internal calcium and drive keratinocyte differentiation. Positively regulates insulin-induced translocation of SLC2A4 to the cell membrane in adipocytes (By similarity). Together with PIP5K1C has a role during embryogenesis (By similarity). Independently of its catalytic activity, is required for membrane ruffling formation, actin organization and focal adhesion formation during directional cell migration by controlling integrin-induced translocation of the small GTPase RAC1 to the plasma membrane. Also functions in the nucleus where it acts as an activator of TUT1 adenylyltransferase activity in nuclear speckles, thereby regulating mRNA polyadenylation of a select set of mRNAs.
Tractability: Small molecule: a high-quality ligand is known; it belongs to a druggable protein family. Antibody: its Gene Ontology location is reachable by antibodies, with high confidence; UniProt places it where antibodies can reach, with medium confidence; the Human Protein Atlas places it where antibodies can reach. PROTAC: UniProt records ubiquitination sites on it; ubiquitination databases record sites on it; a small molecule that binds it is known.
Target class: Kinase; Enzyme
Gene: Protein-coding gene on chromosome 1 (151,197,949 to 151,249,538, forward strand). Ensembl gene ENSG00000143398.
Subcellular location: Cell membrane; Cytoplasm; Nucleus; Nucleus speckle; Cell projection, ruffle; Cell projection, lamellipodium
Subcellular location (Human Protein Atlas): Cytosol; Plasma membrane; Nucleoplasm
Pathways (Reactome):
Metabolism: Synthesis of PIPs at the plasma membrane
Signal Transduction: PI5P, PP2A and IER3 Regulate PI3K/AKT Signaling
Gene Ontology:
Molecular function: 1-phosphatidylinositol-4-phosphate 5-kinase activity; kinase binding; protein binding; 1-phosphatidylinositol-3-phosphate 5-kinase activity; 1-phosphatidylinositol-5-kinase activity; phosphatidylinositol kinase activity
Biological process: actin cytoskeleton organization; cell chemotaxis; focal adhesion assembly; phosphatidylinositol phosphate biosynthetic process; phospholipid biosynthetic process; protein localization to plasma membrane; ruffle assembly; cell migration; keratinocyte differentiation; phagocytosis; phosphatidylinositol biosynthetic process; regulation of phosphatidylinositol 3-kinase/protein kinase B signal transduction; phosphatidylinositol metabolic process
Cellular component: cytosol; focal adhesion; lamellipodium; nuclear speck; nucleoplasm; nucleus; plasma membrane; ruffle membrane; cytoplasm; ruffle
Genetic constraint (gnomAD): Loss-of-function variants: 25 observed, 46.38 expected, observed/expected ratio (o/e) 0.54, 90% interval 0.39 to 0.75. The upper end of that interval is the gene's LOEUF score, 0.75, which puts it in group 3 of 6, group 1 being the genes least tolerant of losing a copy. Missense variants: 366 observed, 566.03 expected, observed/expected ratio (o/e) 0.65, 90% interval 0.59 to 0.7. Synonymous variants: 187 observed, 214.28 expected, observed/expected ratio (o/e) 0.87, 90% interval 0.77 to 0.99.
Homologues: Orthologues: chimpanzee PIP5K1A (99% identical), macaque PIP5K1A (99% identical), dog PIP5K1A (92% identical), pig PIP5K1A (91% identical), rabbit PIP5K1A (91% identical), rat Pip5k1a (88% identical), mouse Pip5k1a (88% identical), guinea pig PIP5K1A (88% identical), zebrafish pip5k1ab (67% identical), Drosophila melanogaster PIP5K59B (53% identical), Drosophila melanogaster sktl (50% identical), Caenorhabditis elegans ppk-1 (48% identical). Paralogues in human: PIP5K1C (63% identical), PIP5K1B (56% identical), PIP4K2B (24% identical), PIP4K2C (24% identical), PIP4K2A (22% identical), PIP5KL1 (18% identical).
Diseases named in the same sentence as PIP5K1A in open-access papers:
PIP5K1A is named in the same sentence as 30 diseases in open-access papers, as found by Europe PMC text mining. Sharing a sentence is not in itself a finding about the gene and the disease. The quoted sentences say what the papers report.
breast carcinoma (8 papers, 2016 to 2024). "PIP5K1α has been directly linked in both breast cancer and prostate cancer (PCa), and researchers have shown that greater levels correspond with worse patient outcomes." (PMID 36473840, 2022). "In addition, high level of PIP5K1α protein was linked to luminal breast cancer subtype with high-grade and poor prognosis." (PMID 30104711, 2019). "Furthermore, elevated level of PIP5K1A mRNA was associated with poor DFS in luminal A subtype of breast cancer." (PMID 30104711, 2019). "Thus, overexpression of PIP5K1α in breast cancer is associated with its gene amplification and poor prognosis in triple-negative breast cancer patients." (PMID 30104711, 2019). "Silencing of PIP5K1α sensitizes breast cancer cells to tamoxifen treatment, which in turns blocks ERα signaling." (PMID 33275817, 2021). "Our study was the first to show the clinical significance of PIP5K1α in breast cancer subtypes, particularly in the triple-negative breast cancer." (PMID 30104711, 2019). "To study the involvement of PIP5K1α in breast cancer, we tested the effect of PIP5K1α inhibitor ISA-2011B on breast cancer cell growth." (PMID 30104711, 2019). "As in prostate cancer, PIP5K1α plays such a role in breast cancer via its kinase activity to produce PIP2, which activates the PI3K/AKT pathway." (PMID 30104711, 2019). "In breast cancer it was shown that PIP5K1A gene copy numbers, together with other genes such as AKT3, PI4KB and PI3KC2B in an amplification stretch in chromosome 1q, are increased in a large percentage of tumors." (PMID 30555634, 2018). "This is in congruence with published findings showing that a large percentage of breast cancers have amplification of chromosome 1q genes, including PIP5K1A." (PMID 30555634, 2018). "Expression of PIP5K1α protein was detected in breast cancer tissues of various subtypes." (PMID 30104711, 2019). "We wanted to study if PIP5K1α could regulate the PI3K/AKT pathway and whether PIP5K1α is associated with ER signaling in ER+ breast cancer." (PMID 30104711, 2019). "In this study, we show that PIP5K1α may be able to play a significant role in breast cancer progression and metastasis." (PMID 30104711, 2019). "In conclusion, we demonstrate that multiple genes, including PIP5K1A, NCKAP1, and CYFIP1, are effective targets for enhancing MHC-I expression in breast cancer cells." (PMID 39408874, 2024). "Further, PIP5K1α acts on PI3K/Akt and ERα pathways in promoting ERα‐positive breast cancer invasion." (PMID 33275817, 2021). "In this paper, we studied the involvement of PIP5K1α with the PI3K/AKT pathway in triple-negative and luminal ER+ breast cancers." (PMID 30104711, 2019). "Overexpression of PIP5K1α has been detected in MDA-MB-231 cell line, showing its involvement in breast cancer." (PMID 30104711, 2019). "Our results showed that PIP5K1α overexpression significantly promoted proliferation and migratory ability of MDA-MB-231 cells, and such effect in breast cancer was similar to what was found in prostate cancer cell lines such as LNCaP and PC-3." (PMID 30104711, 2019). "Through bioinformatics analysis, we found that PIP5K1A, NCKAP1, and CYFIP1 are highly expressed in breast cancer tumors compared with normal tissues, and higher expression of these genes is correlated with a worse prognosis in breast cancer patients." (PMID 39408874, 2024). "Thus, our study uncovers several unrecognized inter-links among PIP5K1α, PI3K/AKT, ER and cyclin D1 in ER+ breast cancer." (PMID 30104711, 2019). "Furthermore, we verified partially according to KEGG functional enrichment or gene-dependency analysis and figured out multiple genes, including PIP5K1A, NCKAP1, CYFIP1, DIS3, TBP, and EXOC1, as effective gene targets for increasing MHC-I expression in breast cancer." (PMID 39408874, 2024).
breast carcinoma (continued). "Taken together, PIP5K1α inhibition, either by ISA-2011B or siRNA-mediated knockdown, significantly abrogated the activity of ERα and estrogen on inducing the target genes, suggesting a potential of ISA-2011B for targeting ER+ breast cancer with elevated PIP5K1α expression." (PMID 30104711, 2019). "However, our analyses suggested that gene amplification of PIP5K1C is not significant in breast cancer, whereas amplifications of PIP5K1A were detected." (PMID 30555634, 2018).
prostate carcinoma (7 papers, 2019 to 2024). A carcinoma that arises from epithelial cells of the prostate gland. "PIP5K1α promotes prostate cancer cell survival and invasion through regulation of expression of AR in PCa cells." (PMID 34932854, 2022). "We have previously identified a lipid kinase phosphatidylinositol 4-phosphate 5 kinase (PIP5K1α) as an important co-factor of AR to activate transcription of AR target genes for prostate cancer cell proliferation and survival." (PMID 35386201, 2022). "We showed that both tamoxifen and ISA‐2011B exert their on‐target effects on prostate cancer cells by targeting cyclin D1 and PIP5K1α/AKT network and the interlinked estrogen signaling." (PMID 33275817, 2021). "In the present study, we unrevealed the effect of tamoxifen on ERα and PIP5K1α/AKT that are responsible for prostate cancer growth and invasion." (PMID 33275817, 2021). "Previous studies have shown PIP5K1α as an emerging cancer drug target and a biomarker in prostate cancer, and a small molecule PIP5K1α inhibitor with the ability to suppress tumor growth in a castration-resistant prostate cancer xenograft mouse model." (PMID 30104711, 2019). "PIP5K1α has emerged as a promising drug target for the treatment of castration-resistant prostate cancer (CRPC), as it acts upstream of the PI3K/AKT signaling pathway to promote prostate cancer (PCa) growth, survival and invasion." (PMID 35386201, 2022). "Our finding is the first to suggest a new therapeutic potential to inhibit or utilize the mechanisms related to ERα, PIP5K1α/AKT network, and MMP9/VEGF signaling axis, providing a strategy to treat castration‐resistant ER‐positive subtype of prostate cancer tumors with metastatic potential." (PMID 33275817, 2021). "PIP5K1A also exhibited negative correlations with these immune signatures and indicated a poor prognosis in BRCA, CESC, LIHC, PAAD, pheochromocytoma and paraganglioma (PCPG), prostate cancer (PRAD), rectum adenocarcinoma (READ), SKCM, testicular germ cell tumors (TGCT), and thyroid carcinoma (THCA)." (PMID 39408874, 2024).
colon cancer (3 papers, 2021 to 2022). "Taken together, our findings suggest that MakA may target the PI3K/Akt lipid signalling pathway in colon cancer cells by downregulating the expression of PIP5K1α and inhibiting Akt." (PMID 36473840, 2022). "However, a study has reported that circRNA PIP5K1A can promote the development of colon cancer by inhibiting miR-1273a, suggesting that miR-1273a may mediate the biological function of circRNA PIP5K1A in colon cancer." (PMID 33439933, 2021). "In the present study, we evaluated the effects of MakA on the host cell PIP5K1α lipid-signalling pathway and the mechanism by which MakA inhibits cell proliferation and induces cell cycle arrest, particularly in HCT8 colon cancer cells." (PMID 36473840, 2022). "In addition, we examined the level of PIP5K1α in two additional (human DLD1 cells and murine CT26 cells) colon cancer cell lines to investigate whether the effect of MakA would be similar in different cell lines." (PMID 36473840, 2022).
glioma (2 papers, 2021 to 2022). A benign or malignant brain and spinal cord tumor that arises from glial cells (astrocytes, oligodendrocytes, ependymal cells). "CircPIP5K1A originates from the phosphatidylinositol-4-phosphate 5-kinase type 1 alpha (PIP5K1A) gene, which is highly expressed in glioma tissues compared with normal adjacent tissues." (PMID 36142352, 2022). "Therefore, we intended to explore the expression characteristics, function, and related mechanisms of a novel type of circRNA, PIP5K1A, in glioma." (PMID 33413401, 2021).
hepatocellular carcinoma (2 papers, 2023 to 2025). A malignant tumor that arises from hepatocytes. "Some studies have confirmed that, in addition to GBM, PIP5K1A is also involved in human hepatocellular carcinoma (HCC) and non-small-cell lung cancer." (PMID 37759870, 2023).
lung carcinoma (2 papers, 2021 to 2022).
Obesity (2 papers, 2016 to 2017). Accumulation of substantial excess body fat. "Additionally, we identified several genes with cASE that have been associated with diabetes (GIPC1, USP36, RNF213, KCTD12) or obesity (PIP5K1A) (78, 79, 81, –, 83)." (PMID 27709125, 2016).
pancreatic cancer (2 papers, 2018 to 2025). "Furthermore, PIP5K1A depletion specifically reduces oncogenic KRAS signaling and proliferation, and sensitizes pancreatic cancer cell lines to a MAPK inhibitor." (PMID 30194290, 2018).
triple-negative breast carcinoma (2 papers, 2019 to 2022). An invasive breast carcinoma which is negative for expression of estrogen receptor (ER), progesterone receptor (PR), and human epidermal growth factor receptor 2 (HER2). "Overexpression of PIP5K1α was associated with low DFS and increased risk of distant metastasis in triple-negative breast cancer." (PMID 30104711, 2019). "We then examined PIP5K1A mRNA expression in luminal and triple-negative breast cancer subtypes by using patient cohorts from database KM plotter." (PMID 30104711, 2019). "Our findings unravel important roles PIP5K1α may play in proliferation, survival and metastasis of the triple-negative breast cancer by using MDA-MB-231 cell line and in vivo xenograft mouse model." (PMID 30104711, 2019). "Thus, inhibition of PIP5K1α via siRNA on the AKT pathway was equivalent to ISA-2011B treatment in triple-negative breast cancer." (PMID 30104711, 2019). "In addition, it shows the therapeutic potential of PIP5K1α inhibitor ISA-2011B, as it specifically induces apoptosis and inhibits metastasis by blocking the elevated PI3K/AKT pathway in triple-negative breast cancer." (PMID 30104711, 2019).
colorectal cancer (1 paper, 2021). A primary or metastatic malignant neoplasm that affects the colon or rectum. "So far, the involvement of a number of circular RNAs including ciRS-7-A, circITGA7, PIP5K1A, GLIS2, and HIPK3 in the development of colorectal cancer has been identified." (PMID 34479583, 2021).
COVID-19 (1 paper, 2022). A disease caused by infection with severe acute respiratory syndrome coronavirus 2. "Microthrombi-positive versus microthrombi-negative COVID-19 comparisons yielded 4 tier 1 targets: PIP5K1A, STAT3, and VEGFA in fibroblasts and CSNK1A1 in pericytes." (PMID 34905515, 2022).
metastatic cancer (1 paper, 2022). A carcinoma which has spread from the original site of growth to another anatomic site. "We therefore wanted to assess whether elevated level of FcγRIIIa expression might be associated with abnormal PIP5K1α expression in PCa primary and metastatic cancer tissues." (PMID 34932854, 2022). "Spearman’s rank correlation test was performed, which revealed that there was a statistically significant correlation between FcγRIIIa and PIP5K1α protein expression in primary and metastatic cancer tissues from the PCa patient cohorts (R2 = 0.480, P < 0.001)." (PMID 34932854, 2022).
metastatic tumors (1 paper, 2019). "Therefore, VEGF is a candidate to be blocked and controlled and to prevent the activation of the androgen receptor (AR)/phosphatidylinositol 4-phosphate 5-kinase type-1 alpha (PIP5K1α)/AKT/MMP-9/VEGF signaling axis required for cell survival and invasion of metastatic tumors." (PMID 31921634, 2019).